IL1B (interleukin 1 beta)
Diseases named in the same sentence as IL1B in open-access papers (continued):
Sharing a sentence is not in itself a finding about the gene and the disease.
COVID-19 (continued). "Admission IL-1β, and IL-33 were significantly lower, while IL-18 was significantly higher in cases when COVID-19 became more severe, along with significantly decreased FVIII, FXIII and plasminogen." (PMID 40303405, 2025). "More evidence links COVID-19 to cytokine release syndrome, specifically elevated pro-inflammatory cytokines (IL-1β, IL-6, TNF-α, and IL-1α) in extreme cases." (PMID 41293155, 2025). "According to our results, it is reasonable to assume that the induction of EndMT in COVID-19 is also ascribable to the presence of several cytokines secreted by macrophages in CM_S1 medium, including IL-1β, IL-6, TNFα, and IFNγ." (PMID 40943589, 2025). "The impact of the ACE2 rs2074192 gene polymorphism on cytokine production (IL-1β, IL-6, IL-8, and TNF-α) is also significant and should be considered when implementing renin-angiotensin-aldosterone system targeting drugs in COVID-19 therapy." (PMID 40066463, 2025). "Concurrently, interleukins like IL-6, IL-8, IL-10, IL-17, and IL-1β are vital mediators of inflammation and have been shown to correlate with the severity of the disease in COVID-19 cases." (PMID 41585373, 2025). "COVID-19 patient cerebrospinal fluid (CSF) sample presented neuroinflammatory profiles of elevated levels of IL-1β, TNF-α, IL-8, and IL-649,50." (PMID 40760135, 2025). "The results of our study provide further evidence and support the presence of elevated levels of IL–1Ra, IL–1β, and malondialdehyde (MDA) in COVID-19 patients, which are associated with a worse course and prognosis of COVID-19." (PMID 40217938, 2025). "Our scRNA-seq data revealed that, in classical monocytes, most pathways related to cytokine-mediated signaling, IL-1β production, and response to type I IFNs were downregulated in post-COVID-19 pregnant women." (PMID 40661959, 2025). "sST2 levels exhibited strong positive correlations with inflammatory cytokines, particularly IL-1β and hsCRP, suggesting that sST2 serves as a surrogate marker of excessive inflammatory activation in COVID-19." (PMID 40710798, 2025). "As for plasma IL-1β levels in COVID-19 patients, only an initial report showed a marked increase in IL-1β in patients exposed to the Wuhan Huanan Seafood Market." (PMID 40143288, 2025). "This study identified significant associations between genetic variants in the IL1B, IL6, and TNF genes and the severity of clinical outcomes in COVID-19 patients." (PMID 40506975, 2025). "A recent investigation revealed that in a cohort of patients with mild to moderate acute COVID-19, IL-1β levels were elevated during acute infection, with concentrations surpassing those observed in patients with bacterial pneumonia." (PMID 40333142, 2025). "Among the thirteen genotyped variants, six SNPs in the IL1B and TNF genes demonstrated the strongest and most consistent associations with COVID-19 severity, particularly in relation to hospitalization, ICU admission, and mortality." (PMID 40506975, 2025). "COVID-19 is characterized by a dysregulated immune response, leading to the excessive release of pro-inflammatory cytokines such as IL-1β, IL-6, and TNF-α, which contribute to tissue injury and multiorgan dysfunction." (PMID 40710798, 2025). "In contrast, IL1B DORC scores were reduced in steroid-treated severe COVID-19 cases and severe RSV cases (padj = 0.032 and 0.006, respectively)." (PMID 39877087, 2025). "The cytokine storm seen in severe COVID-19—involving elevated levels of interleukins (IL-6, IL-1β) and tumor necrosis factor-α (TNF-α)—increases thrombin generation and fibrin deposition." (PMID 41458994, 2025). "Conclusions: the results of our study provide evidence and support the occurrence of elevated levels of IL–1Ra, IL–1β and MDA in the COVID-19 group of patients, which are associated with a worse course and prognosis of COVID-19." (PMID 40217938, 2025).
COVID-19 (continued). "The cytokine storm, a hallmark of severe COVID-19, is characterized by the uncontrolled release of pro-inflammatory cytokines such as tumor necrosis factor-alpha (TNF-α), interleukin-1 beta (IL-1β), and interleukin-6 (IL-6)." (PMID 40002898, 2025). "This aligns with evidence that monocytes in severe COVID-19 can undergo pyroptosis, a pro-inflammatory form of programmed cell death involving inflammasome activation and IL-1β release." (PMID 40429707, 2025). "Neutrophils from severe COVID-19 cases exhibit a hyperinflammatory profile, with upregulated expression of IL1β, CXCL10, and S100A8, corroborating the findings of cytokine storm syndromes reported in severe COVID-19." (PMID 39928675, 2025). "In COVID-19 patients, there were too much of certain proteins called cytokines, including IL-1β, IL-1RA, IL-7, IL-8, IL-9, IL-10, basic FGF, G-CSF, GM-CSF, IFN-γ, IP-10, MCP-1, MIP-1A, MIP-1B, PDGF, TNF-α, and VEGF." (PMID 40895261, 2025). "Cytokine levels are a crucial factor in the renal pathology of COVID-19 patients, compared to other viral infections, resulting in elevated levels of cytokines such as IL-1β, IL-6, IL-18, and TNF-α." (PMID 40863220, 2025). "This aligns with prior work demonstrating that IL-6 overexpression - alongside TNF-α and IL-1β - correlates with severe-stage monocyte activation in COVID-19, though its independent predictive value was attenuated in comprehensive models." (PMID 41184328, 2025). "A meta-analysis of 77 prospective or retrospective cohort studies in adult patients with COVID-19 showed that IL-1β, IL-2R, IL-4, IL-6, IL-8, IL-10, and IL-17, inflammatory markers, were potential risk factors for severe SARS-CoV-2 infection or mortality." (PMID 40066463, 2025). "Production of inflammatory mediators IL-12p70, IL-6, IL-1β, IL-2, and IL-1ra in individuals with flu-like symptoms and those with COVID-19 was higher among residents in endemic areas than in residents from a control non-endemic area." (PMID 40165959, 2025). "These biomarkers, along with high levels of IL-1β, IL-6, TNF-α, hsCRP, and procalcitonin, are associated with increased severity and mortality in COVID-19 cases." (PMID 39967675, 2025). "Persistent high levels of early response proinflammatory cytokines, including IL-6, TNF-α, and IL-1β, can trigger a cytokine storm in COVID-19 patients." (PMID 40571942, 2025). "In the context of acute respiratory distress syndrome (ARDS) caused by COVID-19, metformin has been reported to inhibit NLRP3 inflammasome activation and IL-1β production in macrophages." (PMID 40405092, 2025). "Elevated IL-1β levels in severe COVID-19 patients is central to innate immune response as it induces the expression of other proinflammatory cytokines." (PMID 39937682, 2025). "Elevated levels of pro-inflammatory cytokines, such as IL-6, IL-1β, and TNF-α, are consistently associated with disease progression and poor prognosis in COVID-19 patients." (PMID 41585373, 2025). "Our data reveal a shift towards a pro-inflammatory M1 phenotype in severe COVID-19 cases, with elevated expression of TNFα, IL1β, CCL2, and CCL3, which are markers of classical activation and inflammation." (PMID 39928675, 2025). "On the other hand, the present study reported that the IL-1β rs1143634 CT and TT genotypes had lower frequencies in COVID-19 cases compared to controls and exhibited a protective effect against COVID-19 mortality." (PMID 39452786, 2024). "In contrast to our earlier clinical trial conducted at the onset of the pandemic, which involved unvaccinated COVID-19 patients, the present study observed predominantly very low levels of IL-1β in most participants." (PMID 39434905, 2024). "COVID-19 as a viral infection, is characterized by unique hyperinflammatory signatures across all types of immune cells, among which is the upregulation of IL-1β-, IL-6, and TNF-α-driven inflammatory responses, especially in severe cases." (PMID 38183501, 2024).
COVID-19 (continued). "In the current study, similar expression levels of IL1B were found in the upper airways and peripheral blood of cases with mild COVID-19." (PMID 39590591, 2024). "The mRNA-LNP COVID-19 vaccine can activate complements and increase the production of proinflammatory cytokines including IL-1α, IL-1β, IL-6, IL-8, IFN-γ, and TNF-α in PBMC cultures." (PMID 39852793, 2024). "In particular, we observed increase inthe levels of cytokines known to contribute to cytokine storms as IL-1β, IL-6, IL-12A, IL-12B, IFN-γ, and TNF-α as well as various chemokines and CSFs upon infection with the COVID-19 variants." (PMID 39759510, 2024). "Lower inflammasome pathway activation was observed with significantly lower gene and protein expression of NLRP3, cleaved caspase-1, ASC and IL-1β among severe COVID-19 patients treated with VitD3." (PMID 38748756, 2024). "COVID-19 induces uncontrolled inflammation, a so-called cytokine storm, including IL-6, IL-1b, IL-2, IL-10, TNF-α and monocyte chemoattractant protein (MCP-1)." (PMID 38732160, 2024). "We then assessed serum IL-1β, IL-1Ra and IL-6 concentrations in COVID-19 patients according to disease severity." (PMID 39882243, 2024). "Shared IL1B- and siERG-upregulated genes were enriched in COVID-19 adverse outcome pathway (WP4891; p-value 1.9 × 10–9)." (PMID 38578680, 2024). "Among the pro-inflammatory cytokines observed in COVID-19 patients, interleukin-6 (IL-6), interleukin-1-beta (IL-1β), interferon-gamma (IFN-γ) and tumor necrosis factor-alpha (TNF-α) are generally associated with illness progression." (PMID 39199315, 2024). "It has also been reported that the constitutive activation of NF-κB and enhanced TNFα, IL-1β, and IL-6 levels is a ubiquitous phenomenon among various cell types in severe COVID-19 patients." (PMID 37872376, 2024). "In COVID-19 patients, the median IL-1β expression is 103 pg/mL, with an IQR, excluding outliers, spanning from 101.00 to 105.00." (PMID 39201618, 2024). "The main inflammatory cytokines and chemokines widely produced by patients with severe forms of COVID-19 are IL-6, IL-8, IL-1β, TNF-alpha, IFN-gamma, MIP1α and 1β, CCL2, CCL5, CCL20, CXCL1, CXCL2, CXCL8, CXCL10, and CXCL17." (PMID 39768136, 2024). "A study conducted in Ukraine found that the rs1143634 variation of the IL-1β gene, in COVID-19 patients, yielded the following genotype frequencies: CC–65.8%, CT–28.2%, and TT–6.0%." (PMID 39452786, 2024). "In particular, NLRP3 and NLRP1 inflammasome activation—as well as the components of its signaling, i.e., CASP1, IL-1β, and IL-18, etc.—show a relationship with the inflammatory factors and disease progression in patients with COVID-19." (PMID 38612539, 2024). "The presence of increased plasma levels of sNLRP3, sCasp1p20 and IL-1 cytokines (IL-1β, IL-18) was demonstrated in hospitalized patients across the spectrum of COVID-19 severity." (PMID 39882243, 2024). "Treatment of bone marrow-derived macrophages with COVID-19 EVs enhanced the M1 phenotype and augmented the production of IL-1β, IL-6, and TNF-α." (PMID 39475319, 2024). "In particular, elevated levels of IL-6, IL-7, IL-10, IL-17, IL-23, TNFα, IFN-γ, IFNα or IL-1β have been found in severe COVID-19 cases and have already profoundly been analysed in recent Meta-Analysis." (PMID 38298642, 2024). "In accordance, the results of the present study showed upregulation of both TNF-α and IL-1β cytokines in COVID-19 patients compared to control subjects." (PMID 38183501, 2024). "Among these, IL-1β as well as IL-6 emerged as particularly significant markers, especially in long COVID-19 patients, pointing towards their key role in driving persistent inflammation and ongoing symptoms following the acute phase of infection." (PMID 39518964, 2024). "Conversely, species such as Bacteroides dorei and Akkermansia muciniphila, which were enriched in the COVID-19 cohort, positively correlated with proinflammatory cytokines IL-1β, IL-6, and CXCL8, potentially exacerbating inflammation." (PMID 39518964, 2024).
COVID-19 (continued). "The COVID-19 EVs group had increased levels of IL-1β, IL-6, and TNF-α compared to the other two groups." (PMID 39475319, 2024). "In accordance with our results, previous studies demonstrated that COVID-19 is associated with elevated levels of TNF, IL-1β, and IL-6." (PMID 38187222, 2024). "The significant downregulation of CD1C and IL1B in the COVID-19 patient group, consistent with the MR analysis results, underscores their potential role as protective genes." (PMID 39622956, 2024). "Raised IL1β at 0–4 weeks after COVID-19 onset was strongly predictive of persistent PASC at 24 weeks after COVID-19 onset, and warrants further exploration as a possible predictive biomarker for PASC." (PMID 39008486, 2024). "Hamster studies have showed that COVID-19 leads to IL-1β and IL-6 expression within the hippocampus and medulla oblongata and is associated with decreased neurogenesis in the hippocampal dentate gyrus which leads to learning and memory deficits." (PMID 39474424, 2024). "Levels of cytokines IL-1β, IL-6 and TNFα and levels of cortisol levels according to COVID-19/PASC status." (PMID 38348267, 2024). "In vitro studies further demonstrated that increasing glucose levels in culture led to a significant rise in viral load, as well as the expression of ACE2 and IL-1β in monocytes infected by COVID-19." (PMID 38287388, 2024). "The CSF2, IFNG, and IL1B expression levels were considerably lower in the COVID-19 than in the Healthy group, while those of IL6R, TLR2, TLR4, and TNF were higher." (PMID 38165854, 2024). "Several studies suggest that IL-1β production is an important factor in inflammatory responses during COVID-19 but mechanisms that control IL-1β production or type-I IFN responses upon SARS-CoV-2 infection remain unidentified." (PMID 38418557, 2024). "We also observed that higher levels of IL1β (and to a lesser extent sCD14, IL13, IL17 and TNFα) at 0–4 weeks were strongly associated with ongoing PASC at 24 weeks after COVID-19 onset." (PMID 39008486, 2024). "Macrophages are involved in the immunopathology observed in fatal COVID-19 patients, and profibrotic macrophages, particularly those containing interleukin 1 beta (IL-1β), can hinder epithelial repair." (PMID 38891078, 2024). "The main cytokines involved in the COVID-19-driven inflammatory response have been identified as interleukin 6 and interleukin 1b (IL-1b)." (PMID 39967901, 2024). "We found early IL1β and BMI at COVID-19 onset to be the strongest predictors of PASC at 21–24 weeks, using Shapley additive explanation values as measures of importance." (PMID 39008486, 2024). "In our investigation, we also observed downregulation of IL1B in individuals affected by COVID-19, consistent with prior findings documented in the scientific literature." (PMID 39622956, 2024). "In contrast, due to impaired PAI-1 induction in the 5G5G genotype, IL-1β-/COVID-19-induced retained free PA establish a profibrinolytic state." (PMID 39281671, 2024). "Cytokine storms, characterized by excessive release of inflammatory cytokines like IL-1β, TNF-α, IL-6, and IFN-γ, are associated with severe COVID-19 and can suppress the HPT axis, leading to decreased TSH secretion." (PMID 40735669, 2024). "To assess the consequences of NLRP3-inflammasome and caspase-1 activation in COVID-19 patients, we measured the levels of IL-1β, IL-1Ra and IL-6 in both BALF and serum of C-ARDS or NC-ARDS patients and in control subjects." (PMID 39882243, 2024). "This process contributes to lymphopenia observed in severe COVID-19 and activates the inflammasome, leading to increased IL-1β levels and neutrophilia." (PMID 39335653, 2024). "Upon activation, the NLRP3 inflammasome promotes the release of pro-inflammatory cytokines, such as IL-1β and IL-18, which are key mediators of the inflammatory response seen in severe COVID-19 cases." (PMID 39720706, 2024).
COVID-19 (continued). "Many cytokines have been reported at elevated levels in COVID-19 cases, including IL1-β, IL-6, IL-7, IL-8, TGF-β and TNF-α." (PMID 38914619, 2024). "This study showed a considerable rise in TNF-α and IL-1β serum levels exclusively in COVID-19 patients with TT rs2070788 TMPRSS2 SNP genotype compared to healthy controls." (PMID 39188881, 2024). "IL-1β was recently revealed among the elevated cytokine levels and was employed to categorize COVID-19 patients as mild, moderate, or severe." (PMID 37742314, 2024). "As with IL-1β secretion, COVID-19 PMNs were less responsive than HC PMNs to nigericin- and LPS-mediated LDH and IL-8 release, respectively." (PMID 39172744, 2024). "Most of the research focused attention on the first COVID-19 wave, in which high concentrations of IL-1β, tumor necrosis factor (TNF)-α, IL-6, IL-10, and interferon γ-induced protein (IP)-10 were observed in patients with severe forms of COVID-19." (PMID 39194742, 2024). "This process results in the development of the acute respiratory distress syndrome (ARDS) in the COVID-19 patients, and it is regulated by cytokines, such as IL-1β and TNF-α." (PMID 38999930, 2024). "The elevated levels of IL-18 and IL-1β were observed in patients with COVID-19, which were related to the severity of the disease." (PMID 38399989, 2024). "IL-1β rs16944, the C/T genotype, showed some sort of vulnerability to develop COVID-19, whereas the T/T genotype was demonstrated to offer a protective function." (PMID 39452786, 2024). "Analysis of the GEO database revealed elevated expression levels of pro-inflammatory cytokine genes, including interleukin-1α (IL-1A), IL-1β, and IL-6, in individuals with severe COVID-19 compared to healthy controls." (PMID 39519351, 2024). "CXCL10, GM-CSF, VEGF, IL-1β and CCL2 were clearly positively associated with a higher COVID-19 severity in elderly patients even after adjustment for age and correction for multiple testing." (PMID 38715114, 2024). "Our data suggested that COVID-19-/IL-1β-driven PAI-1 and plasminogen activator (PA) upregulation enhanced PA/PAI-1 complex formation in the 4G4G genotype, trapping PAs and causing a fibrinolysis shutdown." (PMID 39281671, 2024). "On the other hand, we observed a clear pattern of lower production capacity of TNF-α and IL-1β after COVID-19 vaccination, while the release of IL-1Ra was increased in response to almost all stimuli." (PMID 39744634, 2024). "In patients infected with SARS-CoV-2, increased levels of proinflammatory cytokines, including IL-1β, were found, and these increased cytokines and chemokines mediated infection immunopathogenesis and played important roles in the progression of COVID-19." (PMID 38256071, 2024). "Concentrations were significantly higher in the COVID-19+ cohort except for IL-1β, CXCL1, IL-10 and CXCL8." (PMID 38715114, 2024). "The principle for examining cytokine storm in COVID-19 includes a decline in blood lymphocyte count and elevated systematic inflammatory indicators, along with multiple cytokines, such as IL-1β, IL-6, and TNF-α." (PMID 37742314, 2024). "The level of Interleukin-1β (IL-1β) was elevated in COVID-19 patients compared to controls; however, this increase was determined to be significant only in carriers of the TT genotype." (PMID 39188881, 2024). "The current study aims to investigate the predictive value and diagnostic potential of interleukins IL-10, IL-17A, IL-1β, IL-6, CXCL, and MCP for severe COVID-19 and COVID-19 mortality." (PMID 39062105, 2024). "The utility of compound scores, particularly a weighted sum of IL-6, MCP, CXCL, IL-6, IL10, IL-17A, and IL-1β, were particularly stronger in predicting disease severity, reinforcing the potential of a multifaceted biomarker approach in managing COVID-19." (PMID 39062105, 2024). "In this study, we further explored the relationship between CD1C and IL1B genes discovered in the COVID-19 GWAS dataset and immune infiltration." (PMID 39622956, 2024).